MIR548Z (microRNA 548z)
Synonyms: hsa-mir-548z
Gene: MicroRNA gene on chromosome 12 (64,622,509 to 64,622,605, reverse strand). Ensembl gene ENSG00000266016.
Homologues: Orthologues: chimpanzee ptr-mir-548c (100% identical). Paralogues in human: MIR548H3 (80% identical), MIR548X2 (77% identical), MIR548AZ (76% identical), MIR548AY (75% identical), MIR548AN (73% identical), MIR548AA1 (71% identical), MIR548K (70% identical), MIR548F3 (67% identical), MIR548AX (65% identical), MIR548N (65% identical), MIR548AH (64% identical), MIR548F1 (63% identical), and 13 more.